IL3 (interleukin 3)
Diseases named in the same sentence as IL3 in open-access papers (continued):
Sharing a sentence is not in itself a finding about the gene and the disease.
experimental autoimmune encephalomyelitis (5 papers, 2017 to 2025). An autoimmune demyelinating disease of the central nervous system that is produced experimentally in animals by the injection of homogenized brain or spinal cord in Freund's adjuvant. "However, B10.PL IL-3-deficient mice remained susceptible to experimental autoimmune encephalomyelitis (EAE), a mouse model of MS." (PMID 29915594, 2018). "Very recently, it was reported that IL-7 could promote the development of a unique subset of GM-CSF and IL-3-producing T cells (“Th-GM”) in mice and this was associated with encephalitogenicity in the experimental autoimmune encephalomyelitis model." (PMID 29075267, 2017). "Recent studies showed that astrocyte-secreted cytokines, such as IL3 and IL33, control microglia recruitment and activation, leading to astrocyte pathogenic activation and neuronal injury in AD and EAE (experimental autoimmune encephalomyelitis) subsequentially." (PMID 39886603, 2025).
inflammatory bowel disease (5 papers, 2019 to 2024). A spectrum of small and large bowel inflammatory diseases of unknown etiology. "It has been studied that IL-2, IL-3 and IL-8 expressions (which play an important role in intestinal inflammation such as in inflammatory bowel disease [IBD]) are regulated by NF-κB during CD28 co-stimulation." (PMID 35909996, 2022). "Interestingly, IL-3, a major cytokine produced by activated mast cells in the mucosal layer of the intestines, is significantly reduced in glucocorticoid-treated patients with inflammatory bowel disease (IBD), emphasizing its importance in the immunomodulatory effect during inflammation." (PMID 36980556, 2023).
periodontitis (5 papers, 2014 to 2025). An acute or chronic inflammatory process that affects the tissues that surround and support the teeth. "In particular, GMSCs were treated with a culture containing inflammatory cytokines such as TNF-α, IL-1β, IFN-γ, IFN-α, and IL-3, and an inflammatory animal model was created in one study, ligature-induced periodontitis in mice." (PMID 33628266, 2021). "In the present study, other ratios such as IL17A/IFNgamma, IL17A/IL2, IL17A/IL3 and IL17A/IL4 had significantly higher values in the periodontal patients, reflecting their impact on chronic periodontitis." (PMID 30573746, 2018). "Curiously, however, our results were contrary to those reported by these authors, as four anti-inflammatory cytokines (IFNgamma, IL2, IL3 and IL4) showed significantly higher concentrations in chronic periodontitis than in health." (PMID 28912468, 2017). "In contrast, in the present series, we observed that other ratios, such as IL1beta/IFNgamma, ILbeta/IL2, ILbeta/IL3 and ILbeta/IL4, may play an essential role in quantitative terms in chronic periodontitis." (PMID 30573746, 2018).
colorectal cancer (4 papers, 2020 to 2023). A primary or metastatic malignant neoplasm that affects the colon or rectum. "Elevated serum IL-3 levels have been observed in patients with colorectal cancer as compared to healthy controls." (PMID 37275910, 2023). "DEGs manifested several interesting functions, with respect to the experimental setup, where they appeared to participate in response to drug functions, the relaxin signaling pathway, colorectal cancer, the NF-κB survival pathway and IL3 signaling pathway." (PMID 34072627, 2021). "Some authors reported that colorectal cancer could have eosinophilic infiltration, and that colorectal cancer had the potential for expression of various chemokines, such as interleukin (IL)-2, IL-3, IL-5, CCL (CC chemokine ligand) 11, or CCL24, that trigger eosinophil development and migration." (PMID 33109117, 2020).
diabetes (4 papers, 2016 to 2025). "In NOD mice, exogenous IL-3 delayed diabetes onset and reduced disease incidence when administered during early life (2–4 weeks of age)." (PMID 40804870, 2025). "Bone marrow cells obtained from IL-3-treated mice protected other mice from cyclophosphamide-induced diabetes." (PMID 27781209, 2016). "IL-3 is a “good” IL in terms of glucose metabolism, presenting defensive effects in experimental diabetes." (PMID 27781209, 2016). "Administration of IL-3 twice weekly starting at 2–4 weeks of age delayed the onset and reduced the overall incidence of diabetes in mice." (PMID 27781209, 2016). "This can be an explanation for overexpression of IL-3 in diabetes patients." (PMID 27781209, 2016). "Further analysis revealed that IL-3 exposure promotes the generation of a distinct population of immature T cells (Thy-1+ CD3εlo CD4− CD8− CD25−) in the bone marrow, capable of delaying diabetes onset upon adoptive transfer." (PMID 40804870, 2025). "A similar positive association has been previously reported between systemic inflammation, i.e., increased serum cytokine IL-1 β, IL-3, INF- γ, and GADA levels in patients with both types of diabetes and significantly higher IL-6 and IL-15 concentrations in autoimmune diabetes." (PMID 37025699, 2023). "Thus, overexpression of IL-3 in T2DM patients can have both protective and damaging effects: protective for diabetes and yet damaging for heart and vascular." (PMID 27781209, 2016). "Similarly, CD14+DN cells from patients with diabetes produced significantly less IL-8 (P < 0.05 for comparison to NoDR; P < 0.001 for DR patients), while HGF and IL-3 secretion was only significantly less in the DR group (P < 0.001, and P < 0.01, respectively)." (PMID 38983045, 2023).
glioma (4 papers, 2022 to 2023). A benign or malignant brain and spinal cord tumor that arises from glial cells (astrocytes, oligodendrocytes, ependymal cells). "REACTOME analyses further indicated IL4/IL3 pathways among associated genes, which can induce a shift towards immune-suppressive M2 phenotype of macrophages, linked to poor outcome in glioma." (PMID 35158950, 2022). "qRT-PCR assay demonstrated the upregulation of TNF-α, IL-2, IL-3, and IL-4 expression, whereas the downregulation of IL-12 expression in HK2-knockdown glioma cells, suggesting that HK2 is essential for glioma development through regulating immune infiltration." (PMID 35982398, 2022). "Therefore, to further confirm our hypothesis, we next examined the expression of several key inflammatories and immune modulators, including TNF-α, IL-2, IL-3, IL-4, and IL-12, in HK2-silenced T98 and GBM1 glioma cells." (PMID 35982398, 2022).
ischemic stroke (4 papers, 2019 to 2025). A stroke disorder caused by obstruction of blood flow to the brain, due to thrombotic (local blood clot formation) or embolic (due to a blood clot or other material traveling from another site) event. "Receiver Operating Characteristic (ROC) analysis showed that salivary basic FGF, HGF, IL-3 and LIF can distinguish ischemic stroke patients from the control group with high sensitivity and specificity." (PMID 40221607, 2025). "In this study, we demonstrated that the concentrations of basic FGF, HGF, IL-3, and LIF most effectively differentiate ischemic stroke patients from the control group (AUC = 1, sensitivity and specificity = 100%)." (PMID 40221607, 2025). "Unfortunately, no studies that we are aware of have attempted to relate alterations of IL-3 and CCL12 to neutrophil infiltration following ischemic stroke." (PMID 30853895, 2019).
pancreatic cancer (4 papers, 2018 to 2022). "In a mouse model of pancreatic cancer, basophils recruited to tumor draining lymph nodes were activated by T cell-derived IL-3 to produce IL-4, promoting Th2 cell and M2 macrophage differentiation which favors pancreatic cancer development." (PMID 35693800, 2022). "Pharmacological inactivation of PI3Kα in three different mutant Kras pancreatic cancer cell lines significantly and reproducibly decreased IL3 levels." (PMID 34033220, 2021).
cognitive decline (3 papers, 2022 to 2025). "The authors concluded that microglial activation is a major causal factor, as its removal prevented cognitive decline and reduced a broad spectrum of cytokines (IL-1α, IL-1β, IL-3, IL-4, IL-5, GM-CSF)." (PMID 41155372, 2025). "In addition, our study found that higher baseline CSF IL-3 were associated with reduced cognitive decline." (PMID 36578067, 2022). "Microglia sensitized by astrocyte-derived IL-3 clear Aβ aggregates, thus rendering IL-3 among crucial mediators of astrocyte–microglia crosstalk to resist AD progression and cognitive decline." (PMID 38012702, 2023). "Moreover, mediation analysis revealed that CSF IL-3 modulated the level of CSF sTREM2 and contributed to tau pathology (as measured by CSF p-tau/t-tau) and subsequent cognitive decline." (PMID 36578067, 2022). "Furthermore, the effect of Aβ pathology on cognitive decline was partially mediated by the pathway from CSF IL-3 and CSF sTREM2 to tau pathology." (PMID 36578067, 2022).
Cognitive impairment (3 papers, 2018 to 2026). Abnormal cognition is characterized by deficits in thinking, reasoning, or remembering. "Furthermore, we found that the concurrence of CSF IL-3, CSF sTREM2, and CSF p-tau/t-tau synergistically mediated the progression from Aβ deposition to the development of cognitive impairment." (PMID 36578067, 2022). "It indicates that IL-3 may be a major factor in the spreading from Aβ pathology to tau pathology to cognitive impairment." (PMID 36578067, 2022).
dengue (3 papers, 2012 to 2025). "To summarize, transgenic expression of SCF, GM‐CSF, and IL‐3 in NSG BLT mice resulted in improved human myeloid cell reconstitution, enhanced B cell maturation, and antigen‐specific antibody responses to dengue virus infection." (PMID 27980777, 2016). "Patients with severe dengue disease and those with acute Japanese encephalitis exhibited excessively high levels of proinflammatory cytokines, known as a cytokine storm, including GM-CSF, TNF-α, IL-3, IL-6, and IL-8/CXCL8." (PMID 39972499, 2025). "In summary, we found that patients with severe dengue had lower T cell numbers but that DV-NS3 specific T cells produced high levels of IFNγ but not IL-3, IL-13, IL-2, IL-10 or IL-17." (PMID 23209731, 2012). "We found that whilst patients with severe dengue had lower total T cell numbers, the DV-NS3 specific T cells persisted and produced high levels of IFNγ but not TNFα, IL-3, IL-13, IL-2, IL-10 or IL-17." (PMID 23209731, 2012).
erythroleukemia (3 papers, 2022 to 2025). Acute erythroid leukemia characterised by the presence of at least 50% erythroid precursors and at least 20% myeloblasts in the bone marrow. "TF-1 is a human erythroleukemia cytokine-dependent cell line that proliferates only in the presence of human GM-CSF or IL-3." (PMID 36680222, 2023). "Each Db‐Fc was assessed by flow cytometry for binding to TF‐1 cells, which are derived from a human erythroleukemia, display endogenous EPOR, and only grow in the presence of either EPO, granulocyte‐macrophage colony‐stimulating factor (GMCSF), or interleukin 3 (IL‐3)." (PMID 40960423, 2025).
fibrosarcoma (3 papers, 2013 to 2020). A malignant mesenchymal fibroblastic neoplasm affecting the soft tissue and bone. "Our early studies using fibrosarcoma tumor models demonstrated that the expression of the IL-3 gene within tumors could enhance the immunogenicity of classically non-immunogenic tumors, leading to the development of long-term immunity even after the primary tumor was regressed by irradiation." (PMID 23441198, 2013).
food allergies (3 papers, 2023 to 2025). "Interleukin 3 (IL-3), interleukin 5 (IL-5), and interleukin 13 (IL-13) were cytokines produced in a statistically significant way by peripheral blood mononuclear cells stimulated in vitro with cow’s milk in patients with food allergies." (PMID 37763228, 2023).
gastric cancer (3 papers, 2020 to 2025). A primary or metastatic malignant neoplasm involving the stomach. "CCL5, CCL22, CCL21, CCL2, and CCL15 were correlated with effector memory CD4 T cell in T1/T2 stage gastric cancer, and the number of cells was associated with the expression of IL3, IL17F, IL18, IL22, and IL31." (PMID 33426088, 2020). "Notably, the secretion of Interleukin 3 (IL-3) in Yes-associated protein 1 (YAP1) overexpressing and 5-FU-resistant gastric cancer cells induces tumor-associated macrophages to undergo M2-type polarization, promoting their GLUT3 expression and activating glycolysis." (PMID 40264038, 2025).
Hypercholesterolemia (3 papers, 2016 to 2023). An increased concentration of cholesterol in the blood. "Fostamatinib impaired hypercholesterolemia-associated monocytosis stimulated by GM-CSF and IL-3 in Apoe−/− mice." (PMID 26891724, 2016). "Although the precise mechanism responsible for the increased CBS expression at the cell surface remains elusive, hypercholesterolemia appears to disrupt a negative feedback desensitization response that downregulates CBS in response to IL3 or GM-CSF stimulation." (PMID 32086626, 2020).
Insulin resistance (3 papers, 2020 to 2024). Increased resistance towards insulin, that is, diminished effectiveness of insulin in reducing blood glucose levels. "Interestingly, six of the cytokines elevated in 3n mice that were attenuated with the Ch+ diet (IL-1α, IL-1β, IFN-γ, TNF-α, IL-3, and IL-6) have been associated with the development of insulin resistance in T2D." (PMID 39683562, 2024).
leishmaniasis (3 papers, 2018 to 2021). Infectious disease that is transmitted through the bite of hematophagous female phlebotomine sand flies. "In contrast, IL-3 promotes the infection in murine model of CL highlighting the species-specific differences in the role of IL-3 in leishmaniasis." (PMID 31024534, 2019).
lung fibrosis (3 papers, 2020 to 2023). "Modules 1 to 5 are most closely linked to the lung fibrosis pathway, IL-3 signaling pathway, oxidative stress pathway, Aryl hydrocarbon receptor pathway, and Nrf2 pathway, respectively." (PMID 33066647, 2020). "Both IL-4 and IL-3 are related cytokines that regulate many aspects of inflammation and have been reported to involve into the inflammatory responses of pulmonary fibrosis." (PMID 34711217, 2021). "Afterward, we used Metascape for the pathway enrichment analysis of this network, and we found that the most significant terms within the cluster consisting of EGF, IL-1β, IL-3, TNF-α, CCL2 were associated with lung fibrosis and proinflammatory/fibrotic mediators." (PMID 36733673, 2023).
lupus nephritis (3 papers, 2019 to 2025). Glomerulonephritis in the context of systemic lupus erythematosus. "More recent studies have shown that IL-3 has a detrimental role in experimental autoimmune encephalitis and myocarditis, lupus nephritis, sepsis, and blood-stage malaria and a beneficial role in anti-tick immunity." (PMID 31356170, 2019).
mastocytosis (3 papers, 2018 to 2023). A clonal myeloproliferative neoplasm characterized by the proliferation and accumulation of neoplastic mast cells in one or multiple organs or organ systems. "Therefore, IL-3, produced by T cells and basophils, has also been associated with basophilia and mastocytosis in such infections." (PMID 37275910, 2023). "Because IL-3 and IL-9 induce mucosal mastocytosis, we examined the capacity of mice injected with IL-2 and IL-18 to protect against infection with S. venezuelensis." (PMID 30717382, 2019). "IL-18 induces mastocytosis by increasing the mast cell growth factor IL-3, thereby promoting the elimination of S. venezuelensis." (PMID 30717382, 2019). "Because IL-3 and IL-9 induce mucosal mastocytosis, we examined whether the animals developed mucosal mastocytosis after treatment with IL-2 and IL-18." (PMID 29731751, 2018).
neutropenia (3 papers, 2019 to 2024). A decrease in the number of neutrophils found in the blood. "IL-3 levels are stimulated by P-MAPA therapy, and this increase might be protective for patients during OC chemotherapy; administration of rhIL-3 to patients with platelet count < 75,000/mm3 is effective to fight thrombocytopenia and neutropenia after chemotherapy." (PMID 31861351, 2019).
preeclampsia (3 papers, 2014 to 2025). Preeclampsia is a hypertensive disorder of pregnancy that is characterized by new-onset hypertension with proteinuria presenting after 20 weeks of gestation, and depending on mild or severe forms may initially present with severe headache, visual disturbances, and hyperreflexia. "The aim of this study was to evaluate the predictive value of maternal inflammatory status, assessed through biomarkers of inflammation (CRP, chorioamnionitis, preeclampsia), and neonatal inflammatory markers (CRP 1, CRP 2, PCT, IL3, MMP9) on the incidence of NEC in preterm neonates." (PMID 40295408, 2025).
sarcoidosis (3 papers, 2014 to 2025). Sarcoidosis is a multisystemic disorder of unknown cause characterized by the formation of immune granulomas in involved organs. "Our in silico analyses also revealed that IL-3 and IL-5 pathways, which signal via the shared βc receptor, are concurrently activated in progressive lung sarcoidosis, with the combined (IL-3, IL-5, and GM-CSF) pathway exhibiting the highest enrichment in both GSEA and GSVA results." (PMID 41476976, 2025).
T cell lymphoma (3 papers, 2013 to 2024). "Cells tested included the IL-3-dependent murine pro-B cell line, Baf3, the IL-2-dependent human T cell line, Kit225, and the human T cell lymphoma cell line, HH." (PMID 27444277, 2016).
thyroid cancer (3 papers, 2019 to 2025). "In contrast, thyroid cancer signalling, CXCR4, ILK, IL-8, IL-3, JAK/STAT and mTOR signalling pathways were significantly enriched in GWASLN6." (PMID 41520521, 2025). "In the GWASLN6, thyroid cancer signalling, as well as the CXCR4, ILK, IL-8, IL-3 and the JAK/STAT signallings, were statistically enriched." (PMID 41520521, 2025). "Tumor-related leukocytosis caused by the release of cytokines such as granulocyte colony-stimulating factor (g-csf), granulocyte-macrophage colony-stimulating factor (gm-CSF), IL-1a,b, IL-3, IL-6, and TNF-α and its prognostic effect have been described in various cancers, including thyroid cancers." (PMID 40004836, 2025). "The detailed mechanism of inhibiting migration and invasion by nevirapine in dedifferentiated thyroid cancer cells was not performed in our study, but the next part of our work will be to explore in depth how nevirapine works to inhibit migration and invasion by IL‐3/STAT3 pathway." (PMID 31631580, 2019).
acute graft versus host disease (2 papers, 1983 to 2024). A syndrome of immunologically mediated tissue damage that may occur following an allogeneic transplant, usually affecting the skin, liver, and GI tract. "This means that our study did not have the opportunity to widen its considerations on more cytokines such as IFN-γ, G-CSF, GM-CSF, IL-2, IL-3, IL-5, and IL-13, which all have a known role in acute GVHD." (PMID 39728035, 2024). "We have investigated the in vivo production of IL-3 in mice rendered leukaemic with WEHI-3b cells and mice stimulated by acute graft versus host disease (GVHD)." (PMID 6411109, 1983).
allergic contact dermatitis (2 papers, 2023). An inflammatory skin condition caused by an immune response to direct contact between the skin and an allergen. "Using a hapten fluorescein isothiocyanate (FITC)-induced allergic contact dermatitis (ACD) mouse model, we show that basophils in FITC-treated IL-3-knockout mice are defective in crossing the vascular endothelium to enter the inflamed skin." (PMID 37180157, 2023).